KRT16 (keratin 16)
Description:
Epidermis-specific type I keratin that plays a key role in skin. Acts as a regulator of innate immunity in response to skin barrier breach: required for some inflammatory checkpoint for the skin barrier maintenance.
Synonyms: K16; KRT16A; NEPPK; CK16; FNEPPK; K1CP; PC1
Tractability: Antibody: its Gene Ontology location is reachable by antibodies, with medium confidence. PROTAC: ubiquitination databases record sites on it; its protein half-life has been measured.
Gene: Protein-coding gene on chromosome 17 (41,609,778 to 41,615,899, reverse strand). Ensembl gene ENSG00000186832.
Subcellular location (Human Protein Atlas): Intermediate filaments
Pathways (Reactome):
Developmental Biology: Formation of the cornified envelope; Keratinization
Gene Ontology:
Molecular function: protein binding; structural constituent of cytoskeleton; structural constituent of skin epidermis; structural molecule activity
Biological process: hair cycle; negative regulation of cell migration; cytoskeleton organization; establishment of skin barrier; inflammatory response; innate immune response; intermediate filament organization; keratinization; keratinocyte differentiation; keratinocyte migration; morphogenesis of an epithelium
Cellular component: cytoskeleton; extracellular exosome; nucleus; cytosol; intermediate filament; keratin filament; cornified envelope
Genetic constraint (gnomAD): Loss-of-function variants: 43 observed, 47.08 expected, observed/expected ratio (o/e) 0.91, 90% interval 0.71 to 1.18. The upper end of that interval is the gene's LOEUF score, 1.18, which puts it in group 5 of 6, group 1 being the genes least tolerant of losing a copy. Missense variants: 560 observed, 628.69 expected, observed/expected ratio (o/e) 0.89, 90% interval 0.83 to 0.95. Synonymous variants: 225 observed, 258.68 expected, observed/expected ratio (o/e) 0.87, 90% interval 0.78 to 0.97.
Homologues: Orthologues: chimpanzee KRT16 (93% identical), macaque KRT16 (89% identical), rabbit KRT16 (87% identical), mouse Krt16 (84% identical), rat Krt15 (83% identical). Paralogues in human: KRT14 (83% identical), KRT17 (66% identical), KRT15 (64% identical), KRT13 (59% identical), KRT10 (58% identical), KRT19 (55% identical), KRT12 (54% identical), KRT24 (54% identical), KRT9 (52% identical), KRT27 (49% identical), KRT28 (48% identical), KRT36 (47% identical), and 56 more.
Diseases named in the same sentence as KRT16 in open-access papers:
KRT16 is named in the same sentence as 114 diseases in open-access papers, as found by Europe PMC text mining. Sharing a sentence is not in itself a finding about the gene and the disease. The quoted sentences say what the papers report.
psoriasis (84 papers, 2005 to 2026). An autoimmune condition characterized by red, well-delineated plaques with silvery scales that are usually on the extensor surfaces and scalp. "Histopathological changes were assessed using hematoxylin and eosin staining, while molecular alterations were examined by RT-qPCR analysis of psoriasis-associated keratin genes (Krt16, Krt17, and Krt6a) and evaluation of JAK-STAT signaling activity." (PMID 41976231, 2026). "Krt16 is a cytoskeleton protein and is mainly associated with congenital thick nail disease, psoriasis, and other skin diseases." (PMID 37452012, 2023). "KRT6 and KRT16 are considered to be hyperproliferation-associated keratins and to be the hallmarks of psoriasis." (PMID 30180891, 2018). "For instance, among transcripts increased significantly in human psoriasis, we identified 26 transcripts associated with the “epidermis development” (GO:0008544) gene ontology term (e.g., KRT16, KRT17, ELF3)." (PMID 21483750, 2011). "A different KRT16 expression is also associated with psoriasis development." (PMID 37109658, 2023). "The mRNA expression of Krt6, Krt14, and Krt16 which are associated with hyper-proliferation of keratinocytes, and of antimicrobial peptide S100a8, which is correlated with psoriasis severity, were significantly increased by imiquimod treatment in the vehicle (PBS)-injected group." (PMID 26901187, 2016). "Keratin 16 (KRT16) expression is induced in hyperkeratotic lesions as well as atopic dermatitis or psoriasis, and a specific role in the regulation of immune response has been proposed." (PMID 40243580, 2025). "A crosstalk between non-coding RNAs (ncRNAs) associated with psoriasis and “stress keratins” K6, K16, and K17 (encoded by the genes KRT6, KRT16 and KRT17, respectively)." (PMID 41296428, 2025). "The downregulated genes detected at day 14 in these populations included inflammatory molecules (e.g., IL36G, S100A7/A8/A9) and structural proteins (GJB2, KRT16/17), known to be over-expressed in the upper layers of the psoriasis epidermis." (PMID 38291032, 2024). "Keratin 16 has also been shown to contribute to the hyperproliferation of keratinocytes in psoriasis, and silencing keratin 16 leads to a reduction in VEGF secretion by psoriatic keratinocytes." (PMID 39194725, 2024). "Keratin 16 (K16) and keratin 17 (K17) are established markers of excessive keratinocyte hyperproliferation in psoriasis and are known to promote T-cell activation and psoriasis development." (PMID 38007430, 2023). "At the same time, CB1 activation suppressed the expression of two damage-induced keratins, keratin 6 and keratin 16, which are highly upregulated in hyperproliferative disorder psoriasis." (PMID 35955938, 2022). "Free gallic acid on psoriasis-like skin disease in vivo and in vitro models reduced the mRNA expression of keratin 16 and keratin 17, two biological markers of psoriasis." (PMID 36364354, 2022). "Cytokeratin 16 (CK16), a hallmark of psoriasis, was barely detectable in normal epidermal tissue and was significantly upregulated in the cytoplasm of PN and PP biopsies." (PMID 34199748, 2021). "Comparable to our study, an upregulation of Krt16 was demonstrated in a three-dimensional psoriasis mouse model." (PMID 34440590, 2021). "The expression of cytokeratin 16 is upregulated in the lesional epidermis of psoriasis patients and in keratinocytes incubated with IL-17A." (PMID 32070069, 2020). "Because Krt16 expression is a marker of keratinocyte hyperproliferation in psoriasis, this observation further corroborates the persistence of acanthosis observed in DK mice at d7." (PMID 32345660, 2020). "This study shows the possibility of using psoriasin, nestin, Krt16, and IL-21 as biochemical markers of psoriasis and highlights the correlation of these with biomarkers of obesity (BMI, leptin, and resistin)." (PMID 31275060, 2019).
psoriasis (continued). "The objective was to establish if psoriasin, nestin, Krt16, and IL-21 were possible biomarkers of psoriasis and to correlate them with Body Mass Index (BMI), leptin, and resistin (biomarkers of obesity)." (PMID 31275060, 2019). "The current study supports the conclusion that keratin 16 and keratin 17 expression in keratinocytes were upregulated by Stat3-dependent mechanisms, accelerating the development of psoriasis." (PMID 26893174, 2016). "Epidermal thickness, proliferative activity (Ki-67 expression) and cytokeratin 16 expression are generally considered good markers of psoriasis activity." (PMID 20017943, 2009). "Prior studies have shown that cytokeratin-6, cytokeratin-16, and cytokeratin-17, within the same family as CK-19, are upregulated in psoriasis, leading to excessive keratinocyte proliferation – supporting the involvement of the keratin system in this condition." (PMID 38813379, 2024). "Moreover, keratin 16 has been suggested to be a potential marker of treatment response not only in psoriasis but also in PM." (PMID 38132857, 2023). "Even though PM was expected to share a similar gene expression profile with SCC, due to the high incidence of this neoplasm in PM lesions (7.6%), more similarities between PM and psoriasis have been observed (highly upregulated keratin 16, S-100 molecules [A7, A8 and A9] and connexin 26)." (PMID 38132857, 2023). "Therefore, Keratin 6 (K6) and Keratin 16 (K16), described as close molecular correlates of psoriasis severity, were used." (PMID 37226685, 2023). "These protective effects of gallic acid on psoriasis were related to an unexpected downregulation of Nrf2, which targeted keratin 16 and keratin 17, ameliorating the psoriasis area, the severity index scores, and the epidermal hyperplasia induced by the psoriasis-like disease in mice." (PMID 36364354, 2022). "Four of the top six keratins (Krt16, Krt17, and Krt6a and b) that were increased in mice lacking epidermal Pparg are keratins that are known to serve as alarmins and are up-regulated in wound healing and psoriasis." (PMID 34445339, 2021). "In psoriasis patients, the neutralization of IL-17A by ixekizumab or secukinumab significantly decreases histological acanthosis, the number of Ki-67+-proliferating keratinocytes, and epidermal cytokeratin 16 expression." (PMID 32070069, 2020). "However, in the rERDR1-injected group, the expression of Krt6, Krt14, Krt16 and S100a8 was significantly decreased, demonstrating that rERDR1 inhibits the induction of psoriasis-like skin inflammation by imiquimod." (PMID 26901187, 2016). "Among them, 10 genes including the inhibitor of DNA binding 4 (ID4), heparin binding protein 17 (HBP-17), keratin 16 (KRT16), S100A2, S100A9, S100A12, guanine nucleotide binding protein 15 (GNA15), MTX, PRKMK3, and SCYA2 were all found to be localized in the psoriasis susceptibility loci." (PMID 26362816, 2015). "Keratin 16 is upregulated in epidermal diseases such as psoriasis." (PMID 16321154, 2005). "In addition, TPA treatment of ILEI‐overexpressing skin lead to elevated expression of Keratin 16 (K16), a pathological marker, known to be upregulated also in psoriasis as analyzed in total skin protein extracts and by qPCR on freshly sorted primary keratinocytes." (PMID 37226685, 2023). "In psoriasis explants, SHIN1 decreased the expression of Ki67, Keratin 16, and pro-inflammatory cytokines including IL-17A, IL-22, and IFN-γ." (PMID 42103703, 2026). "In conditions such as psoriasis and lichen planus, stress-induced keratins (KRT6, KRT16, and KRT17) are highly upregulated, contributing to keratinocyte hyperproliferation, migration, and acting as epithelial alarmins that amplify immune signaling." (PMID 41479908, 2025). "Total RNA was extracted and analyzed using qRT-PCR to assess the expression levels of psoriasis-related keratinocytes marker genes (KRT6, KRT16) and CD-related inflammatory cytokines (IL6, IL8, TNF-α)." (PMID 40406126, 2025).
psoriasis (continued). "The core NB-UVB downregulated DEGs included a few psoriasis signature genes, such as IL36G, DEFB4A/B (coding human β defensin 2), S100A15, SERPINB4, KRT16, KRT6A, and DSC220." (PMID 36928592, 2023). "In conclusion, NB-UVB normalizes psoriatic plaques by suppressing the expression of psoriasis signature genes, such as IL36G, DEFB4A/B, S100A15, SERPINB4, KRT16, and KRT6A in, both, the PE and CE skin." (PMID 36928592, 2023). "To confirm that skin damage and psoriasis were induced in our AD-HSE, we examined KRT10 and KRT16 expression." (PMID 35216228, 2022). "A series of psoriasis-related genes, such as S100A8, S100A9, KRT6A (keratin 6A), KRT6B, KRT6C, KRT16, and MMP9 (metalloproteinase 9), were also down-regulated." (PMID 35273606, 2022). "The results are comparable to studies with gallic acid, a natural small molecule from radix of Paeoniae rubra, that also suppressed IL17A-mediated KRT16 and 17 expression in HaCaT cells and in an IMQ-psoriasis mouse model in vivo." (PMID 33801280, 2021). "The common over-expressed genes found in both cSCC and psoriasis were: DEFB4 (defensin B4), SERPINB3, STAT1, K16 (keratin 16), WNT5A, and CEACAM5." (PMID 34267747, 2021). "Gallic acid (GA), a natural small molecule from Radix Paeoniae Rubra with an anti-psoriatic effect, has been shown to suppress IL17A-mediated KRT16 and KRT17 expression by preventing activation of Nrf2 in vitro and in the IMQ-psoriasis mouse model in vivo." (PMID 31374826, 2019). "Nrf2, a transcription factor that is overexpressed in keratinocytes in skin cancer, ichthyosis skin diseases and in psoriasis, has been identified as an important factor promoting keratinocyte hyperproliferation through inducing KRT17 and KRT16." (PMID 31374826, 2019). "Some of the genes found to be commonly upregulated in psoriasis and skin SCC, such as ADAM23, Krt16 (cytokeratin 16) and IVL (involucrin), were also found to be upregulated in 3 week TPA treated skin (data not shown)." (PMID 19432991, 2009). "In cellular models, Etoposide demonstrated promising therapeutic effects by significantly downregulating the expression of psoriasis-related keratinocytes marker genes (KRT6, KRT16) and CD-related inflammatory cytokines (IL6, IL8, TNF-α), highlighting its potential in treating psoriasis and CD." (PMID 40406126, 2025). "Cytokeratin 16 (CK16) and S100A7, are common psoriasis marker also used in the clinic." (PMID 40678130, 2025). "Additionally, NB‐UVB modulates the oxidative stress response and results in suppression of psoriasis signature gene expression (e.g., IL 36G, DEF4A/B, S100A15, KRT16, and KRT6A)." (PMID 40908513, 2025). "In contrast, keratin expression in psoriasis highlights distinct stress-responsive keratins—including Keratins 6A-C (KRT6A-C), Keratin 16 (KRT16), and Keratin 17 (KRT17)—which serve as molecular markers indicating keratinocyte activation and cellular stress responses." (PMID 41479908, 2025). "QPCR analysis revealed that knockdown of LINC01206 led to increased expression of hyperproliferation markers KRT6, KRT16, and KRT17, suggesting that LINC01206 may promote aberrant keratinocyte proliferation in psoriasis." (PMID 40670887, 2025). "Bimekizumab treatment completely reversed the levels of cytokines/chemokines, anti‐microbial peptides, or proliferation‐related molecules, such as CXCL8, CCL20, IL‐17A, IL‐17F, IL‐17C, keratin 16, IL‐36γ, DEFB4, or S100A7, in psoriasis lesional skin to the levels of non‐lesional skin." (PMID 38482898, 2024). "Further psoriasis and AD share the KRT6A, KRT6B, KRT6C, KRT16, KRT17 as their common DEGs." (PMID 35874668, 2022). "Interestingly, stress keratinocytes expressing KRT6, KRT16, and S100A8/9 have been identified in the human epidermis of psoriasis and melanomas, raising the possibility that they can play a wide variety of roles in the diseased skin TME." (PMID 35653192, 2022).
psoriasis (continued). "Studies have shown that KRT17, but not KRT6 or KRT16, plays a role in driving keratinocyte hyperproliferation during wounding or psoriasis." (PMID 31374826, 2019). "The process of psoriasis in the scalp induces expression of keratin 16 in the interfollicular epidermis and acrotrichial epithelium, but it does not further induce keratin 16 expression in follicular keratinocytes that constitutively express this keratin." (PMID 26849645, 2016). "In addition, the expression of psoriasis-related inflammatory response markers, including Keratin 16, S100A8, and S100A9, was not reduced by anti-FGFR2IIIb treatment." (PMID 39919800, 2025). "Importantly, Krt16, a marker of hyperproliferation of keratinocytes in psoriasis did not belong to the top 30 up-regulated genes but was still up-regulated in an IL-36–dependent, KC36-independent manner in Aldara-treated ears at d7." (PMID 32345660, 2020). "Finally, increased KRT16 (K16) expression was found in psoriasis (scalp and skin), similar to AD, but without a significant decrease in other hair keratins." (PMID 26849645, 2016).
pachyonychia congenita (15 papers, 2016 to 2025). Pachyonychia congenita (PC) is a rare genodermatosis predominantly featuring painful palmoplantar keratoderma, thickened nails, cysts and whitish oral mucosa. "Consistent with a recent study, oxidative stress and dysfunctional NRF2 underlies the palmoplantar keratoderma disorder pachyonychia congenita associated with K16 mutations, with SFN treatment reducing the aberrant keratinisation in krt16−/− mice." (PMID 29523849, 2018). "The Keratin 16 protein participates in innate barrier function of the skin, and hereditary mutations in KRT16 gene are associated with pachyonychia congenita, hyperkeratotic lesions of the skin, nails and oral epithelium." (PMID 29420561, 2018). "Missense mutations at the KRT16 locus can cause pachyonychia congenita-associated PPK or focal non-epidermolytic PPK." (PMID 35854363, 2022). "Pachyonychia congenita (PC, OMIM #167200, #167210, #615726, #615728, and #615735) is a rare autosomal dominant disorder caused by keratin gene mutations in KRT6A, KRT6B, KRT6C, KRT16 or KRT17." (PMID 34724947, 2021). "Pachyonychia congenita (PC) is a rare hereditary condition affecting keratinization, which results from an underlying genetic mutation in one of the five keratin genes: KRT6A, KRT6B, KRT6C, KRT16, or KRT17." (PMID 40686559, 2025).
breast carcinoma (14 papers, 2015 to 2025). "Through in silico analysis, a positive correlation between KRT16 gene expression and shorter relapse-free survival was shown in two large breast cancer patients’ data sets." (PMID 34359774, 2021). "Only KTR14, KRT16, CXCL9, and CFD in BRCA1 Ovarian Cancer and TSPAN7 and CDKN2C in BRCA2 ovarian cancers were highly upregulated, and KANK4, MFGE8, LINC00346, and SA100A1 in BRCA1 mutated breast cancer, and MAGEA4 in BRCA2 breast cancers." (PMID 40647506, 2025). "Enhanced KRT16 expression is significantly correlated with lower overall survival in metastatic breast cancer patients, while TFF1 is closely associated with bone metastasis in estrogen receptor (ER) + breast cancer." (PMID 38254021, 2024). "Overexpression of KRT16 enhances cell motility and promotes breast cancer metastasis." (PMID 36118853, 2022). "Because one of the characteristics of breast cancer cells with a mesenchymal-like phenotype is increased migration properties, we assessed whether knockdown of KRT16 impacts cell migration." (PMID 34359774, 2021). "This hypothesis is substantiated by the reported upregulation of KRT16 in tumors of the salivary glands, laryngeal, squamous skin and breast cancer." (PMID 29420561, 2018). "Interestingly, keratin 16 upregulation is also a common phenomenon in basal-like breast cancer cell lines." (PMID 25962645, 2015). "Many of these are enzymes or cytoskeletal proteins (ANXA1, KRT10, KRT16, TUBB, ACTB, ACTA1, PKM2, and HSPA8) that have been previously reported as able to induce autoantibodies with diagnostic potential across different tumor types, including PDAC, breast cancer, and neuroblastoma." (PMID 30651550, 2019). "In addition, four cytokeratin genes (KRT8, KRT16, KRT17, and KRT19) and eight tumor-associated genes (TERT, MUC16/M17S2/CA125, CD44, TWIST1, TACSTD1/EpCAM/CD326/ESA/HEA125/GA733, DPP4/CD26, ESR1, and PGR), were upregulated in CRC and breast cancer samples." (PMID 29882767, 2018). "Some genes associated with cell adhesion were analyzed from this radiation- and estrogen-induced experimental breast cancer model, including E-cadherin gene CDH1, DSC3, GJA1, the Integrin alpha 6 gene ITGA6, the Integrin beta 6 gene ITGB6, the Keratin genes KRT14, KRT16, KRT17, KRT6B, and LAMB3." (PMID 36293530, 2022).